EPAS1 (endothelial PAS domain protein 1)
Diseases named in the same sentence as EPAS1 in open-access papers (continued):
Sharing a sentence is not in itself a finding about the gene and the disease.
chronic mountain sickness (9 papers, 2017 to 2025). A pathological condition resulting from chronic exposure to hypoxia at high altitude. "A paradigmatic example of this evolutionary mechanism is offered by the EPAS1 gene, whose most frequent haplotype in Himalayan highlanders was proved to reduce their susceptibility to chronic mountain sickness and to be introduced in the gene pool of their ancestors by admixture with Denisovans." (PMID 39513938, 2024). "The low prevalence of chronic mountain sickness showed a correlation with a signal of selective sweep in the EPAS1 gene and unelevated HGB in Tibetan highlanders." (PMID 36244759, 2022). "Taken together, it is suggested that EPAS1 gene variant may be a secondary adaptive mechanism useful to reduce risk of developing chronic mountain sickness in populations at high-altitude, but not the mechanism of increasing the fitness of Tibetan individuals." (PMID 36244759, 2022).
rheumatoid arthritis (9 papers, 2014 to 2022). A chronic, systemic autoimmune disorder characterized by inflammation in the synovial membranes and articular surfaces. "EPAS1 is the gene that expresses HIF-2α, which is also deeply involved in the pathophysiology of rheumatoid arthritis." (PMID 35366946, 2022).
Right ventricular hypertrophy (8 papers, 2013 to 2025). In this case the right ventricle is more muscular than normal, causing a characteristic boot-shaped (coeur-en-sabot) appearance as seen on anterior- posterior chest x-rays. "Coincidentally, Hu demonstrated mice with EPAS1 inducible deletion by antisense oligonucleotides (EPAS1-ASO) exhibited a decreased right ventricular hypertrophy index, reduced vascular remodeling and increased survival of PH." (PMID 36923253, 2023). "Zimmer reported a small molecule inhibitor of HIF-2α, C76, facilitates the binding of Iron Regulatory Protein 1 (IRP1) to the IRE of EPAS1 message and abolishes EPAS1 translation, showing as a potential strategy ameliorating the vascular remodeling and right ventricular hypertrophy in PH." (PMID 36923253, 2023).
asthma (7 papers, 2021 to 2025). "Immune analysis revealed that EPAS1 is closely associated with immune cell infiltration in asthma." (PMID 40165005, 2025). "In conclusion, CYBB, EPAS1, CBS, G6PD, and STAT3 demonstrate strong diagnostic potential for asthma." (PMID 40165005, 2025). "This study aims to better understand how the JAK2/STAT3/EPAS1 axis regulates inflammation and ferroptosis in asthma." (PMID 40165005, 2025). "Our investigation also identified important genes involved in ferroptosis and asthma, including EPAS1, STAT3, G6PD, CYBB, and CBS." (PMID 40165005, 2025). "The AUC value of FKBP5 (AUC = 0.832), WNT5A (AUC = 0.813), TM4SF1 (AUC = 0.769), PDK4 (AUC = 0.753), EPAS1 (AUC = 0.748) and GMPR (AUC = 0.705) was more than 0.7, which suggesting higher diagnostic value for asthma." (PMID 36550577, 2022). "CYBB (AUC ═ 0.82), EPAS1 (AUC ═ 0.839), CBS (AUC ═ 0.804), G6PD (AUC ═ 0.86), and STAT3 (AUC ═ 0.873) demonstrate high diagnostic accuracy for asthma (AUC > 0.8)." (PMID 40165005, 2025). "Notably, these findings highlight the JAK2/STAT3/EPAS1 axis as a potential therapeutic target for asthma, offering new insights into its molecular mechanisms and identifying novel biomarkers for diagnosis and treatment." (PMID 40165005, 2025). "Furthermore, it seeks to investigate the regulatory role of the JAK2/STAT3/EPAS1 axis in ferroptosis in asthma." (PMID 40165005, 2025). "In summary, IL-13 may promote ferroptosis and inflammation by activating JAK2/STAT3 and EPAS1, leading to 16HBE cell damage and potentially contributing to asthma progression." (PMID 40165005, 2025). "FKBP5, WNT5A, TM4SF1, PDK4, EPAS1 and GMPR had potential diagnostic value for asthma." (PMID 36550577, 2022). "Further comparison of the expression of marker genes in all cell subtypes in control and asthma revealed marker genes like DCN, COLOA1, COX4L2, CLEC3B, EPAS1 and POSTN belonging to stromal cells remained the most variable genes." (PMID 36439114, 2022).
atherosclerosis (7 papers, 2022 to 2024). A disease characterized by the build-up of fatty material and calcium deposition in the arterial wall resulting in partial or complete occlusion of the arterial lumen. "We then measured EPAS1 levels in EC of the mouse aortic arch, which is known to generate disturbed flow associated with atherosclerosis initiation." (PMID 39234692, 2024). "Surprisingly, our murine model demonstrates that endothelial EPAS1 exhibits a protective effect against atherosclerosis at an atheroprone region exposed to LOSS." (PMID 39234692, 2024). "To analyze the role of Epas1 in atherosclerosis, we generated Epas1EC-KO and control Epas1EC-WT mice, which were treated with AAV-PCSK9 and exposed to a HFD for 8 weeks to generate hypercholesterolemia." (PMID 39234692, 2024). "En face staining revealed EPAS1 enrichment at sites of disturbed blood flow that are prone to atherosclerosis initiation." (PMID 39234692, 2024). "In summary, our findings underscore the preferential expression of EPAS1 at atheroprone sites, where it reduces atherosclerosis by promoting fatty acid metabolism to support endothelial repair." (PMID 39234692, 2024). "Here, we investigate the role of EPAS1 in atherosclerosis development, particularly at disturbed flow sites." (PMID 39234692, 2024). "We demonstrate that EPAS1 is enriched in these regions, where it limits atherosclerosis by promoting fatty acid metabolism to enhance endothelial homeostasis." (PMID 39234692, 2024). "Endothelial EPAS1 attenuates atherosclerosis at sites of disturbed flow by maintaining EC proliferation via fatty acid uptake and metabolism." (PMID 39234692, 2024). "The role of Epas1 in atherosclerosis was evaluated by inducible endothelial Epas1 deletion, followed by hypercholesterolemia induction (adeno-associated virus-PCSK9 [proprotein convertase subtilisin/kexin type 9]; high-fat diet)." (PMID 39234692, 2024). "However, it should be noted that this model mimics features of early atherosclerosis and that further research using other models (eg, ApoE−/−) is required to fully appreciate the role of Epas1 in disease progression." (PMID 39234692, 2024). "Identifying mechanisms that shift the balance of HIF transcription factors to suppress HIF1 and enhance EPAS1 may offer therapeutic opportunities to promote vascular repair and reduce atherosclerosis." (PMID 39234692, 2024). "By contrast, we hypothesize that EPAS1+ HIF1A− cells are programmed for homeostatic proliferation that slows the initiation of atherosclerosis." (PMID 39234692, 2024). "The transcription factor EPAS1 (HIF2A) has regulatory roles in endothelium, but its involvement in atherosclerosis remains unexplored." (PMID 39234692, 2024).
cardiomyopathy (7 papers, 2018 to 2025). A disease of the heart muscle or myocardium proper. "Collectively, these results support that EPAS1 plays a causal role in the development of cardiomyopathy." (PMID 40034852, 2025). "Further research is required to decipher whether drug-mediated control of EPAS1 induction would be sufficient to impede or prevent disease development in DSP-cardiomyopathy and in ACM associated with genetic defects in other desmosomal genes." (PMID 40034852, 2025). "Together, these findings highlight the potential of spatial transcriptomics as a powerful tool for linking molecular processes to local remodeling responses and indicate EPAS1 as a critical molecular driver of cardiomyocyte degeneration in the context of DSP-cardiomyopathy." (PMID 40034852, 2025). "We then proceeded to compare the expression of stemness genes in different groups of cardiomyopathies using the same method, and screened for the same high expression of CD34, EPAS1, and MYC." (PMID 38799173, 2024). "Lastly, while this paper highlights EPAS1 involvement in DSP-cardiomyopathy progression, it does not address the precise mechanism by which a loss in DSP protein levels induces EPAS1 expression." (PMID 40034852, 2025). "To investigate whether EPAS1, BNIP3L, and SOD2 induction is a common feature of cardiomyopathy, we also assessed the levels in additional patient hearts with mutations in PKP2 and phospholamban (PLN), associated with ACM and DCM." (PMID 40034852, 2025). "the results showed that EPAS1 and MYC had high expression in N, and we hypothesized that EPAS1 and MYC had a possible correlation with the improvement of cardiomyopathy." (PMID 38799173, 2024). "Because EPAS1 was densely and highly expressed in C3 AGT + Fibroblasts, and MYC was densely but poorly expressed in C3 AGT + Fibroblasts, whether inhibition or promotion of EPAS1 and MYC is beneficial to the treatment of cardiomyopathy requires further study." (PMID 38799173, 2024). "Additionally, stemness genes EPAS1 and MYC, along with the regulator FOS, may play roles in modulating the biological processes of cardiac fibroblasts in cardiomyopathy." (PMID 38799173, 2024).
Infertility (7 papers, 2021 to 2026). "Whether EPAS1 is involved in endometriosis-associated infertility may be a new research direction for the future." (PMID 41188339, 2025).
fibrosarcoma (6 papers, 2015 to 2025). A malignant mesenchymal fibroblastic neoplasm affecting the soft tissue and bone. "On the other hand, HIF-2α has been reported to suppress tumor growth in undifferentiated pleomorphic sarcoma, fibrosarcoma, and dedifferentiated liposarcoma, where EPAS1 is largely considered to be epigenetically silenced." (PMID 37124944, 2023). "Decreased EPAS1 messenger RNA (mRNA) expression (with no copy number variation) was detected in the majority of STS patient samples analysed, including UPS, fibrosarcoma and liposarcoma." (PMID 26837714, 2016).
sarcoma (6 papers, 2012 to 2021). A usually aggressive malignant neoplasm of the soft tissue or bone. "Together, these results suggest that HDACs specifically suppress EPAS1 in sarcoma, and that re-expressing EPAS1 could be a mechanism underlying HDACi's inhibition of sarcoma growth." (PMID 26837714, 2016). "Loss of HIF-2α (encoded by the EPAS1 gene) increased sarcoma tumour cell proliferation." (PMID 26837714, 2016). "Analysis of TCGA sarcoma patient samples revealed that 25% of all human sarcomas have lost at least one copy of EPAS1, while 67% remain diploid." (PMID 26837714, 2016). "Many cancers, including STS, contain altered epigenetics, and our findings define an epigenetic mechanism whereby EPAS1 is silenced during sarcoma progression." (PMID 26837714, 2016). "We also analysed DNA methylation along the EPAS1 locus in the TCGA sarcoma data set, and found no consistent methylation changes in the samples." (PMID 26837714, 2016). "Given that HIF-2α expression opposes STS tumourigenesis, we sought a class of compounds that could induce re-expression of HIF-2α in sarcoma cells, and found that the FDA-approved HDACi SAHA (Vorinostat) reactivates EPAS1 expression in STS cells, inhibiting sarcoma progression." (PMID 26837714, 2016).
soft tissue sarcoma (6 papers, 2017 to 2023). A malignant neoplasm arising from muscle tissue, adipose tissue, blood vessels, fibrous tissue, or other supportive tissues excluding the bones. "More, studies have shown that the expression level of HIF-2α gene EPAS1 in human soft tissue sarcomas (STS) is lower than that of the corresponding normal tissue." (PMID 33109235, 2020). "On the other hand, recent evidence showed that in HIF-2a inhibits high-grade soft tissue sarcomas cell growth in vivo, suggesting a cell context-dependent role for EPAS1 in tumor development." (PMID 28533480, 2017). "In soft tissue sarcoma (STS), SAHA/vorinostat can upregulate EPAS1/HIF2A expression but not HIF1A expression." (PMID 38276269, 2023).
cervical cancer (5 papers, 2017 to 2025). A primary or metastatic malignant neoplasm involving the cervix. "A number of malignancies are linked to dysregulation of EPAS1 expression, which also controls ferroptosis in clear cell and cervical cancers." (PMID 40165005, 2025). "EPAS1 can promote the proliferation, migration, and invasion of cervical cancer cell lines and inhibit apoptosis." (PMID 38722283, 2024). "Endothelial PAS domain‐containing protein 1 (EPAS1) contributes to the progression of cervical cancer." (PMID 38722283, 2024). "The identification of the super‐enhancers upstream of EPAS1 helps us to explore the mechanism of occurrence and development of cervical cancer, and further deepen our understanding of the role of super‐enhancers in cervical cancer." (PMID 38722283, 2024). "We detected 23 cervical cancer tissues and 20 normal cervical tissues by qPCR, and the results showed that EPAS1 mRNA was highly expressed in cervical cancer tissues (F = 34.910, p < 0.001)." (PMID 38722283, 2024). "EPAS1 is highly expressed in cervical cancer tissues and promotes the proliferation, invasion and migration of cervical cancer cells while inhibiting apoptosis." (PMID 38722283, 2024). "The WB assay showed that EPAS1 was highly expressed in cervical cancer tissues (t = 2.816, p = 0.023)." (PMID 38722283, 2024). "EPAS1 promotes malignant behaviour of cervical cancer cells." (PMID 38722283, 2024). "EPAS1 overexpression can reduce cisplatin sensitivity by excessive autophagy in cervical cancer." (PMID 38722283, 2024). "qPCR and WB were used to investigate the expression of EPAS1 in normal and cervical cancer tissues." (PMID 38722283, 2024). "We also analysed EPAS1 and immune cell infiltration of cervical cancer." (PMID 38722283, 2024). "EPAS1 could promote the proliferation, invasion, and metastasis of cervical cancer and inhibit the apoptosis of cervical cancer cells." (PMID 38722283, 2024). "Our study showed that EPAS1 was highly expressed in cervical cancer." (PMID 38722283, 2024). "EPAS1 was significantly overexpressed in cervical cancer tissues." (PMID 38722283, 2024). "EPAS1 may be a target for the diagnosis and treatment of cervical cancer." (PMID 38722283, 2024). "Therefore, as an HFRG, EPAS1 plays an important role in cervical cancer." (PMID 38722283, 2024). "Therefore, EPAS1 may be a target for medical diagnosis and treatment of cervical cancer." (PMID 38722283, 2024). "EPAS1, an HFRG, is significantly overexpressed in cervical cancer." (PMID 38722283, 2024). "The expression and role of EPAS1, an HFRG, in cervical cancer were studied." (PMID 38722283, 2024).
congenital heart disease (5 papers, 2018 to 2024). A heart disease that is present at birth. "It is known that hypoxic exposure, either through high altitude or disease, such as congenital heart disease or sickle cell disease, increases the risk for somatic EPAS1 PVs and subsequent PPGL development." (PMID 38481600, 2024). "Somatic/mosaic EPAS1 mutations have also been described in PPGLs arising on a background of cyanotic congenital heart disease." (PMID 33300499, 2021). "Mutations in the EPAS1 coding sequence are associated with several kinds of human diseases, including syndromic congenital heart disease (CHD)." (PMID 30487161, 2018).
endometrial cancer (5 papers, 2006 to 2026). Primary or metastatic malignant neoplasm involving the endometrium (mucous membrane that lines the endometrial cavity). "In endometrial cancer, a spatially separated vascular CAFs subgroup characterized by high levels of MYH11, ESAM, MCAM, and EPAS1 was a poor prognostic factor for patients with endometrial cancer." (PMID 39764562, 2025). "Thus mutual relationships in the expression of both HIF1A and EPAS1 and VEGFA but also with other genes and proteins could be of importance also in endometrial cancer progression." (PMID 39888575, 2026).
familial erythrocytosis (5 papers, 2014 to 2023). "It is possible that the variant described as “benign” for familial erythrocytosis may be associated with a decrease in EPAS1 activity." (PMID 37568921, 2023). "Conversely, HIF2A (EPAS1) gain-of-function mutations can predispose to PH; a Hif2a variant in high altitude cattle increases susceptibility to brisket disease, whilst a HIF2A mutation causing familial erythrocytosis is also associated with elevated systolic PAP in humans." (PMID 31119132, 2019). "A review of the literature on recently reported mutations in patients with non-MPN erythrocytosis, highlighted the role of some known genes associated with familial erythrocytosis, such as EPO, HBB, VHL EGLN1, EPAS1, and EPOR." (PMID 36290845, 2022). "Other variants of EPAS1 have been previously reported to be benign for familial erythrocytosis because they decrease gene function and are positive for familial erythrocytosis because the overexpression of EPAS1 is a key factor in uncontrolled erythrocyte proliferation." (PMID 37568921, 2023). "Other variants of EPAS1 have been previously reported as benign for familial erythrocytosis because they decrease gene function, and they have been revealed to be positive for familial erythrocytosis because the overexpression of EPAS1 is a key factor in uncontrolled erythrocyte proliferation." (PMID 37568921, 2023).
invasive breast carcinoma (5 papers, 2010 to 2024). A carcinoma that infiltrates the breast parenchyma. "It has additionally been demonstrated that there is an estrogen dependent downregulation of EPAS1 in ER+ but not ER- HBC and proposed EPAS1 as a negative prognostic marker in HER2+ invasive breast cancer, since overexpression of EPAS1 worsen the prognosis in HER2 and ER+." (PMID 33218035, 2020).
acute myeloid leukemia (4 papers, 2022 to 2023). Acute myeloid leukemia (AML) is a group of neoplasms arising from precursor cells committed to the myeloid cell-line differentiation. "However, the prognostic and diagnostic values of EPAS1 in acute myeloid leukemia (AML) remain unknown." (PMID 37124944, 2023).
colon adenocarcinoma (4 papers, 2015 to 2024). "Interestingly, we found that EPAS1 copy number variation (CNV) impacted the infiltration levels of B cells, CD8+ T cells, CD4+ T cells, macrophages, neutrophils and dendritic cells in colon adenocarcinoma (COAD) data." (PMID 37994607, 2024).
colorectal adenocarcinoma (4 papers, 2008 to 2025). The most common type of colorectal carcinoma. "Expression of EPAS1 mRNA was correlated with the clinicopathological factors such as T‐stage, N‐stage, presence of associated adenoma, use of pre‐operative chemo‐radiotherapy and the ethnic origin of patients with colorectal adenocarcinomas." (PMID 34250767, 2021).
colorectal tumor (4 papers, 2015 to 2025). "In the colorectal tumour, EPAS1 expression associated with immune infiltrating cells in both COAD and READ data." (PMID 37994607, 2024). "At the same time, we analysed the correlations between EPAS1 expression and the levels of immune infiltrating cells in the colorectal tumour." (PMID 37994607, 2024).
Hyperglycemia (4 papers, 2012 to 2026). An increased concentration of glucose in the blood. "En face staining revealed that EPAS1 expression at the LOSS region of the aorta was unaltered in streptozotocin-treated mice, indicating that hyperglycemia is insufficient to suppress EPAS1." (PMID 39234692, 2024). "Although streptozotocin can cause EC dysfunction, we did not observe a reduced expression of EPAS1 in streptozocin-treated mice that subsequently developed hyperglycemia." (PMID 39234692, 2024).
liposarcoma (4 papers, 2016 to 2023). A usually painless malignant tumor that arises from adipose tissue. "In a separate data set35, decreased EPAS1 mRNA expression correlated with worse overall survival in liposarcoma patients." (PMID 26837714, 2016). "Collectively, these analyses indicate EPAS1 expression is decreased in multiple STS subtypes, and lower EPAS1 levels correlate with poorer prognosis in a cohort of liposarcoma patients." (PMID 26837714, 2016).